MYOF (myoferlin)
Diseases named in the same sentence as MYOF in open-access papers (continued):
Sharing a sentence is not in itself a finding about the gene and the disease.
cancer (continued). "Overall, myoferlin appears to be relevant to exosome biology beyond cancer and this calls for further in depth studies that will in particularly clarify the role of myoferlin in exosomes derived from normal cells." (PMID 27845903, 2016). "The focus of the current study has been placed on cancer cells, because myoferlin expression has been reported to be particularly high in cancer." (PMID 27845903, 2016). "The present study highlights myoferlin as a new functional player in exosome biology, calling for novel strategies to target this emerging oncogene in human cancer." (PMID 27845903, 2016). "Emerging studies demonstrate that myoferlin is frequently overexpressed in cancer, where it promotes cancer cell migration and invasion." (PMID 27845903, 2016). "Myoferlin silencing in both MDA-MB-231 and BxPC-3 cells efficiently reduced myoferlin load in the cancer exosomes." (PMID 27845903, 2016). "In cancer cells, myoferlin overexpression have been shown either at mRNA or protein levels using cancer cell lines or small number of patient tumor samples." (PMID 26919244, 2016). "For this purpose, we treated endothelial cells with PKH67-labelled exosomes, isolated from control and myoferlin-depleted cancer cells." (PMID 27845903, 2016). "The in vitro biomechanical and in vivo tumor formation studies outlined in the current work shed new light on a novel role for MYOF in cancer cell motility and invasion." (PMID 24586247, 2014). "Although tension from the membrane and cytoskeleton act together to limit leading edge protrusions, our current work did not address the molecular mechanisms that underpin the mechanical alternations we observed when MYOF was disrupted in cancer cells." (PMID 24586247, 2014). "Matrigel and collagen I based invasion assays demonstrated that depletion of MYOF diminished the invasive ability of cancer cells." (PMID 22761893, 2012). "The premise that MYOF contributes to cancer invasion was based on several reports implicating a role for ferlin proteins in intracellular vesicle trafficking, including cell motility." (PMID 22761893, 2012). "MYOF has been reported to be involved in proliferation, metastasis, angiogenesis, and the epithelial–mesenchymal transition in various cancer cells." (PMID 39934162, 2025). "Myoferlin is recognized as an emerging oncoprotein, highlighted by the overexpression of myoferlin in several cancer types, including PAAD with the highest expression and the greatest overexpression compared to healthy pancreas (Fig. EV1A)." (PMID 41062852, 2025). "Targeting vesicle trafficking through a protein that is specific or overexpressed in cancer, such as myoferlin, represents an innovative approach to target tumoral vesicle trafficking and could potentially reduce the severity of side toxicity." (PMID 41062852, 2025). "Next, we sought to determine whether apatinib or MYOF knockdown could restrict tumor growth in vivo using an immunocompetent MC38 mouse cancer model." (PMID 39941891, 2025). "Recently, MYOF was identified as a promising biomarker for various cancers, including NSCLC." (PMID 39934162, 2025). "We additionally quantified myoferlin staining in cancer cells on PAAD sections." (PMID 41062852, 2025). "This discovery improves our comprehension of myoferlin localization and function in cancer biology." (PMID 38368370, 2024). "This study improves our comprehension of myoferlin localization and function in cancer biology." (PMID 38368370, 2024). "This could lead to new cancer therapies targeting this protein, which are already underway for myoferlin." (PMID 37538852, 2023). "Because myoferlin has been reported necessary for optimal mitochondrial function, agents targeting myoferlin expression or function may be used in cancer treatment." (PMID 36147922, 2022). "Of these proteins, myoferlin is known to be overexpressed in several human cancers and could be a promising biomarker and therapeutic target for cancer cases." (PMID 34733798, 2021).
cancer (continued). "Although evidence is insufficient yet, MYOF and Rabs may synergistically promote vesicular trafficking in cancer cells." (PMID 33634965, 2021). "Moreover, the anti‐cancer activities of YQ456 were positively correlated with MYOF expression level in transwell invasion assay." (PMID 33634965, 2021). "However, few reports pay attention to the roles of MYOF in endocytosis and exocytosis in cancer cells." (PMID 33634965, 2021). "Thus, a link is emerging between multiple roles of dysferlin and myoferlin in conventional growth and regeneration of skeletal muscle and in oncogenesis, confirming the reprogramming of normal developmental processes in cancer." (PMID 32106631, 2020). "Myoferlin is a ferlin family member protein, mainly known for its physiological function in membrane fusion, and its expression level was correlated with poor survival in several cancer types including PDAC." (PMID 32575867, 2020). "Previous study has shown that nuclear factor of activated T cells (NFAT) can bind to the promoter of MYOF gene and upregulate MYOF expression in fusing myoblasts and damaged MYOF fibers, but little is known about how MYOF gene expression is regulated in cancer cells." (PMID 31828126, 2019). "A mathematical model was proposed to examine the role of myoferlin in cancer cell invasion." (PMID 31443490, 2019). "Targeting MYOF with small interfering RNA and chemical molecules such as WJ460 has demonstrated significant antitumor effects in cancer, indicating that MYOF may be a potential target in the treatment of human cancer." (PMID 31828126, 2019). "MYOF has also been explored in cancers of digestive organs, including pancreas, liver and colon." (PMID 31828126, 2019). "Interestingly, myoferlin was demonstrated to be present in exosomes isolated from several cancer cell types." (PMID 31443490, 2019). "In this context, myoferlin could be considered as a cancer growth promoter as it helps the exocytosis of the growth factors, at least VEGF." (PMID 31443490, 2019). "However, further investigations are still needed to discover the direct link between myoferlin and cancer biology." (PMID 31443490, 2019). "Recently, emerging studies have revealed that MYOF is overexpressed in many cancers." (PMID 31828126, 2019). "Acute myoferlin knockdown may exhibit anti‐angiogenic effects and act as an anti‐angiogenesis target in the treatment of cancer or other angiogenesis‐related diseases." (PMID 31475450, 2019). "The presence of myoferlin in cancer-derived exosomes was verified by electron microscopy." (PMID 27845903, 2016). "Although biochemical approaches are important for defining the molecular details of MYOF function in the context of cancer, increasing emphasis is being directed toward a more holistic set of strategies that include an appreciation of the mechanical principles of tumor cell biology." (PMID 24586247, 2014). "Our work is the first examination of the role of MYOF in cancer cell biology and may shed light on essential features of vesicle shuttling of important cargos within tumor cells that participate in cancer progression and metastasis." (PMID 22761893, 2012). "Structurally, MYOF protein was characterized by multiple functional C2 domains, which have been reported to correlate with the proliferative and metastatic behaviors of cancers, as well as small conserved 60–70 residue Ferlin-specific sequences (FerA, FerB and Ferl domains)." (PMID 36147922, 2022). "Notably, the overexpression of MYOF in sgMYOF cells rescued the anti‐cancer activities of YQ456." (PMID 33634965, 2021). "Myoferlin involvement in PDAC progression could go beyond cancer cell biology." (PMID 32575867, 2020). "The fact that myoferlin is able to determine protein cargo of cancer-derived exosome could explain why this protein is overexpressed in cancer, and further underlines its importance in the regulation of both intra- and extracellular vesicle trafficking of cancer cells." (PMID 27845903, 2016).
cancer (continued). "Antitumor effects observed following myoferlin depletion have been attributed to impaired membrane repair/turnover, the inability to properly internalize growth factor receptors, impaired cancer cell motility and the inability to sustain tumor-associated angiogenesis." (PMID 27845903, 2016). "We unveiled that myoferlin supports COPII-vesicle trafficking and ECM production in CAFs, however myoferlin is also expressed in cancer cells." (PMID 41062852, 2025). "In cancer, the same genes are thus simultaneously correlated with MYOF and ITPR3, tending to show that MYOF and ITPR3 are involved in the same cellular pathways." (PMID 38368370, 2024). "Myoferlin is overexpressed in PDAC and its silencing/targeting has been shown to affect cancer cell proliferation, migration, mitochondrial dynamics and metabolism." (PMID 38368370, 2024). "Remarkably, we identified a positive correlation between myoferlin expression and both c-Met and HGF expression in cancer cells, which corroborates a strong connection between myoferlin and the HGF/c-Met pathway in ccRCC." (PMID 35205843, 2022). "Hence, MYOF might be a promising target for clinical diagnosis and treatment of malignant tumors." (PMID 34957301, 2021). "Remarkably, we have identified a novel MYOF inhibitor YQ456, which exhibits anti‐cancer activities by modulating RTK signaling pathways, endocytosis/exocytosis, and mitochondrial metabolism." (PMID 33634965, 2021). "Then, phosphorylated STAT3 translocates to nucleus chaperoned by MYOF and activates downstream genes of the IL6/STAT3 pathway, thus potentiating tumor cell motility and cancer stem cell phenotype." (PMID 31828126, 2019). "As in other cancer types, HCC required myoferlin to proliferate and perform invasion or anchorage-independent cell growth." (PMID 31443490, 2019). "Previously, we described the overexpression of myoferlin in PDAC and its involvement in cancer cell plasma membrane biology such as exocytosis, endocytosis, and recycling." (PMID 29720728, 2018). "Myoferlin (MYOF), a protein involved in plasma membrane function and repair, is overexpressed in several invasive cancer cell lines." (PMID 29721195, 2018). "Since cytoskeletal mechanics is known to play a critical role in determining cancer cell migratory phenotype, we used AFM and TFM to investigate how MYOF depletion alters cytoskeletal structure, intrinsic stiffness and contractile force generation." (PMID 24586247, 2014). "The absence of a link between cancer cell myoferlin abundance with patient survival was very surprising to us, as previous studies demonstrated that myoferlin ablation in tumor cells impaired tumor size." (PMID 41062852, 2025). "Collectively, these results link stromal myoferlin expression to increased tumor fibrosis (i.e., tumor desmoplasia) and suggest stromal myoferlin rather than cancer cell myoferlin as driver for tumor aggressiveness in PAAD patients." (PMID 41062852, 2025). "While stromal MyofWT tumors were characterized by intense myoferlin abundance in cancer cells and stromal cells, stromal MyofKO tumors lacked stromal myoferlin." (PMID 41062852, 2025). "This was further supported by the absence of a correlation between stromal myoferlin scores and cancer cell myoferlin scores (Fig. EV1K)." (PMID 41062852, 2025). "However, unlike dysferlin, myoferlin has recently also been found to be overexpressed in various human cancers and the altered vesicular trafficking and function of myoferlin has been linked to cancer cell proliferation, metastasis, and resistance to chemotherapy." (PMID 40437073, 2025). "In contrast to stromal myoferlin, a link between cancer cell myoferlin and patient survival was absent." (PMID 41062852, 2025). "Although expression of EPHA7 and myoferlin was not correlated, EPHA7 expression was independently associated with progression-free (HR = 1.237–4.319) and cancer-specific survival (HR = 1.214–4.558)." (PMID 35205843, 2022).
cancer (continued). "Besides, previous immunoprecipitate proteomic analysis demonstrated that Rab GTPase effector Rab‐coupling protein forms a complex with MYOF to regulate RTK trafficking, thus promoting cancer metastasis." (PMID 33634965, 2021). "Furthermore, the prognostic value of MYOF was evaluated using GEPIA and Long-term Outcome and Gene Expression Profiling Database of pan-cancers (LOGpc) database." (PMID 34957301, 2021). "Similar AAV vectors were used as a gene delivery system in cancer, allowing the dream of myoferlin negative-dominant delivery to cancer cells." (PMID 31443490, 2019). "Of note, the functions and mechanisms of myoferlin in cancers have not been thoroughly revealed to date." (PMID 31475450, 2019). "Myoferlin was strongly stained (mainly scores 2 and 3–76% of the cases) in the cytoplasm of cancer cells, whereas no or faintly detectable (mainly scores 0) in adjacent non-tumoural tissue." (PMID 30850580, 2019). "In endometrioid carcinoma, moderate to strong expression of MYOF is observed in normal epithelial tissue and low-grade carcinoma tissue, whereas weak to negative expression is found in high-grade carcinoma tissue." (PMID 31828126, 2019). "Our initial functional analysis showed that myoferlin depletion in cancer cells does not affect exosome quantity but it does affect their size." (PMID 27845903, 2016). "To understand whether the function of myoferlin in CAFs could be different to cancer cells, we performed transcriptomic profiling on MYOFKD cancer cells (PANC1) and crossed the differentially expressed genes (DEGs) between MYOFKD and CTRL cancer cells with DEGs from MYOFKD CAFs." (PMID 41062852, 2025). "Overrepresentation analysis (ORA) of overlapping downregulated DEGs revealed that COPII vesicles and ER-related genes are both downregulated in CAFs and cancer cells upon MYOFKD, suggesting that a COPII-related function of myoferlin may be shared between CAFs and cancer cells." (PMID 41062852, 2025). "Whether MYOF dysfunction in cancer is related to the immune response has not been reported until now." (PMID 34957301, 2021). "The expression levels of MYOF in cancer cells were significantly higher than those in normal cells." (PMID 33634965, 2021). "However, in these cell lines, MFN1/2 immunoprecipitation did not reveal a convincing physical interaction with myoferlin suggesting an interaction specific to cancer cells." (PMID 32575867, 2020). "Decreased cell invasion by MYOF silencing may partially result from down-regulation of several matrix metalloproteinases (MMPs), especially of MMP1, which plays a pivotal role in degrading ECM components to facilitate cancer invasion." (PMID 31828126, 2019). "This suggested that myoferlin could influence exosome cargo content rather than exosome production by cancer cells." (PMID 27845903, 2016). "For further evaluating whether the interactions of MYOF with EGFR and EPHA2 are shared across tumor types, we analyzed MYOF co-expression with the members of common cell membrane receptor kinase (RTK) family from the proteomic data of 375 cancer cell lines from 22 lineages in CCLE." (PMID 34178975, 2021).
tumor (43 papers, 2012 to 2026). "Altogether, the in vivo results above underline the desmoplastic role of myoferlin in CAFs and suggest the pharmacological targeting of myoferlin as new therapeutic approach to tackle tumor desmoplasia in PAAD." (PMID 41062852, 2025). "The results showed that nuclear myoferlin expression is associated with poor overall survival and an increased risk of death, as well as tumor recurrence, perineural invasion, extracapsular spread, a higher T stage, and distant metastasis." (PMID 37538852, 2023). "Myoferlin, a newly identified oncogene, has been associated with tumor metastasis, intracellular ROS production, and energy metabolism." (PMID 36147922, 2022). "Since mitochondrial oxidative phosphorylation has been shown to be implicated in the tumor progression and dissemination, our data identify myoferlin as a valid potential therapeutic target in PDAC." (PMID 31248212, 2019). "MYOF serves as an oncogenic protein implicated in various processes of tumor progression, including tumor cell proliferation, migration, invasion, EMT, angiogenesis, and metastasis." (PMID 31828126, 2019). "Nuclear myoferlin expression was also directly associated with tumor recurrence (p<0.001), perineural invasion (p=0.008), extracapsular spread (p=0.009), higher T-stage (p=0.0015) and distant metastasis (p<0.001)." (PMID 26919244, 2016). "After adjusting for other covariates, myoferlin location, tumor stage and HPV status were significantly associated with overall survival in a multivariable model." (PMID 26919244, 2016). "To test this in vivo, we used a mouse xenograft model to investigate how MYOF loss would affect tumor formation and local invasion." (PMID 24586247, 2014). "Importantly, Myoferlin is upregulated in human PDAC, which is associated with poor patient survival, and Myoferlin ablation abrogates tumor growth in murine PDAC models, highlighting the crucial role of the autophagy-lysosomal pathway in PDAC progression." (PMID 35727403, 2022). "Interestingly, nuclear myoferlin expression was directly associated with high IL-6 expression in the primary tumor samples (p<0.001)." (PMID 26919244, 2016). "In addition, nuclear myoferlin was directly associated with tumor recurrence, perineural invasion, extracapsular spread (ECS), higher T-stage and distant metastasis." (PMID 26919244, 2016). "Thus MYOF loss is associated with a change in tumor formation in xenografts and leads to smaller, less invasive tumors." (PMID 24586247, 2014). "In addition, this same group also revealed that loss of MYOF decreased tumor burden in a mouse xenograft model." (PMID 24586247, 2014). "The reduced invasive capacity of 231MYOF-KD cells led us to study whether proteins associated with tumor-microenvironment interactions may be altered following MYOF depletion." (PMID 22761893, 2012). "In addition, nuclear myoferlin expression was directly associated with high IL-6 expression in the primary tumor samples thereby suggesting that IL-6 might be involved in promoting the nuclear translocation of myoferlin." (PMID 26919244, 2016). "In vivo xenograft experiments demonstrated that MYOF silencing suppressed tumor growth and increased the expression of mitophagy-related proteins BNIP3 and NIX." (PMID 42271528, 2026). "We recently reported that the viral protein, HBZ, activates expression of myoferlin (MyoF), which is overexpressed in several epithelial cancers where it promotes tumor cell metastasis." (PMID 42012183, 2026). "Targeted inhibition of MYOF activates tumor-suppressive mitophagy via the PINK1-Parkin axis, indicating MYOF as a potential therapeutic target in PTC." (PMID 42271528, 2026). "Altogether, this transcriptomic data suggests a link between MYOF expression, stromal activation, and tumor fibrosis in PAAD patients." (PMID 41062852, 2025). "In vivo, knocking down Myoferlin or using apatinib can remodel the tumor microenvironment and enhance sensitivity to immunotherapy." (PMID 39941891, 2025).